TNF (tumor necrosis factor)
Diseases named in the same sentence as TNF in open-access papers (continued):
Sharing a sentence is not in itself a finding about the gene and the disease.
infection (continued). "It is a chemoattractant for fish leukocytes, it stimulates chemokine production in cells following infection and is known to induce expression of TNF-α." (PMID 29588496, 2018). "The levels of IL-1β and TNF-α production increased in a multiplicity of infection (MOI)- and time-dependent manner." (PMID 30078841, 2018). "This suggests the possibility that HDL inhibits phagocytosis of mycobacteria and in turn reduces infection-dependent TNF-α production." (PMID 29712918, 2018). "Infection of IL-10 deficient mice is accompanied by increased release of IFN-γ, TNF-α, IL-12, and RNS." (PMID 30559742, 2018). "TNFα levels in the LDA group peaked at week 3 (day 21) post-infection in a statistically significant manner, but returned to day 14 levels by week 4 (day 28)." (PMID 29740435, 2018). "Among the immunostimulatory cytokines, IL-2, IL-12, TNF-α, and interferons are the most prominent in anti-infection and antitumor activity." (PMID 29854832, 2018). "DGAT1 knockdown led to approximately 50% decrease in infection induced TNFα in the supernatant in case of NM." (PMID 30018616, 2018). "It has been documented that ExoY lowers concentrations of TNF and IL-1β after infection of rat lungs or epithelial cells, respectively." (PMID 29734720, 2018). "From 8 to 15 days post-infection (dpi), Lena-infection induced higher TNF-α and IL-1β detected in the bronchoalveolar lavage fluid (BALF) and blood compared to those induced by Finistere-infection." (PMID 30469357, 2018). "Meanwhile, the expression of NOD2, as well as inflammatory factors IL-1β, TNF-α, and IL-6 was markedly up-regulated in 24 h and 48 h after infection groups." (PMID 30186539, 2018). "Our results showed an increase in mortality in the mice group that received a second dose of the vaccine and presented high levels of TNF-α 49 days post-infection and, consequently, decreased protection (approximately 60%) against the wild-type strain." (PMID 30186241, 2018). "When the pan-HDAC inhibitor TSA was delivered before infection, 76% and 73.4% reductions of TNF-alpha concentration in the supernatant were observed at 200 and 400 nM, respectively." (PMID 29986388, 2018). "The intracellular localization of TAK1 and TABs was unchanged in AGS cells in response to 40 min of infection with H. pylori or to 10 min of stimulation with TNF or IL-1β." (PMID 29581850, 2018). "Tumor necrosis factor (TNF) is a homotrimeric cytokine produced by immune and epithelial cells in response to infection or tissue injury." (PMID 29295985, 2018). "The levels of IL-2 and TNF-α were significantly increased while the level of IL-6 was obviously decreased in the infection group compared with the normal control group." (PMID 30305831, 2018). "Studies involving primary Lm responses describe a role for TNF in primary protection, as TNF neutralization or infection of gene knock-out mice result in increased bacterial burden and increased mortality." (PMID 29438281, 2018). "In a rhesus monkey GBS infection model, increased amniotic fluid TNF-α, IL-1β, and IL-6 occurred before uterine contractility or any clinical signs of infection, suggesting a direct role for infection in triggering preterm labor." (PMID 29520354, 2018). "The levels of IL-12 (p = 0.0101) and TNFα (p = 0.0365) were found to be elevated at 48 h post infection in LdCen−/−-infected DCs." (PMID 29915577, 2018). "TNF-α subsequently activates macrophages, recruits them to the site of infection and participates in granuloma formation." (PMID 30232332, 2018). "PIM/AM-like cells significantly upregulated TNFα expression upon infection, whereas IL-8 and IL-6 were also upregulated, although non-significantly, highlighting the pro-inflammatory role of PIM/AM-like cells upon PRRSV infection." (PMID 29977043, 2018). "The addition of 4 mM VPA to culture medium before infection, significantly induced a 5- and 3-fold reduction in TNF-alpha and IL-6 mRNA expression, respectively." (PMID 29986388, 2018).
infection (continued). "Long-term therapeutic use of anti-TNF carries with it safety issues which include potential for development of skin lesions, immune reactions, peri-operative complications, infections, cancers and decreased fertility/adverse effects on pregnancy." (PMID 30065229, 2018). "The proportion of IFN-γ-producing γδ T cells increased at 6 d post-infection and then decreased thereafter, while that of TNF-α-producing γδ T cells continued to decrease during the infection." (PMID 30619302, 2018). "The production of IL-6 showed a profile similar to that of TNF, with upregulation of IL-6 induced by infection in the WT group only in pregnant females." (PMID 29867817, 2018). "Some of these cytokines (e.g., TNF-α) take part in recruiting more neutrophils or other leukocytes to the site of sterile inflammation or infection." (PMID 29670633, 2018). "In infected macrophages, EV Y decreased production of PGE2 and cytokines TNF-α and IL-6 24 h after infection." (PMID 29755471, 2018). "At 12–72 h after infection with E. coli, the content of pulmonary TNF-α was significantly higher (p < 0.05) in the lean-E." (PMID 30250258, 2018). "The total number of CD8+ T cells, virus-specific Tet-GP33+ CD8+ T cell expansion, and intracellular cytokine (IFN-γ and TNF) production was limited in Ceacam1–/– mice 8 days after infection." (PMID 29967450, 2018). "In accordance with this, we observed an increase in IL-12p40 and TNF-α expression by DCs stimulated with different concentrations of EVs and after infection with S. brasiliensis yeast cells." (PMID 30333803, 2018). "In this experimental setting, we observed that TNF-α production was impeded because of TLR2-deficiency upon BCG and M. tuberculosis infection." (PMID 29712918, 2018). "γδ T cells are also a direct and potent source of critical inflammatory cytokines like IFNγ, TNFα and IL-17A in many pathological contexts, including infection, autoimmune disease and cancer." (PMID 30538697, 2018). "If the person's immune system becomes weakened, for example through TNFα modulating therapy, a serious infection can develop." (PMID 29848389, 2018). "Histology of the liver at the early phase of infection revealed that granuloma surface area was significantly larger for TNF−/− and etanercept-treated mice than other mice (*p < 0.05 vs TNFKi)." (PMID 29184553, 2017). "The liver showed slightly elevated TNFα as well, but we found decreased IL-1β and KC level after the cell wall mutant infection." (PMID 28713338, 2017). "The levels of IFN-β, IL-12p40, and TNF-α in the supernatants were highest 48 h after infection, while the levels of IFN-γ peaked at 24 h after infection and significant levels remained at 48 h." (PMID 28765218, 2017). "This study also found that the effects of TNF were most apparent in the global peripheral response but had little effect on recruitment of CD8+ T cells to the site of infection." (PMID 28886201, 2017). "An adequate production of pro-inflammatory cytokines such as IFN-γ, TNF-α, IL-1, IL-12, and IL-6 is essential for controlling infection by intracellular parasites." (PMID 28572772, 2017). "Action of bLf against E. coli sepsis resulted from the elicitation of IL-1 involved in the production of acute phase proteins, as well as from the amelioration on TNFα levels increased in response to the infection." (PMID 28257033, 2017). "Monocytes of healthy individuals previously treated with IFN-γ produce, after infection with L. donovani, a greater amount of TNF-α, important cytokine in the host response to microbial infection." (PMID 28767981, 2017). "As TT was identified as a high-TBE-risk genotype, this result agrees well with TNFα expression promoting the disease onset and provides a link between the TLR3 expression and the TNFα synthesis during an infection with TBEV in vivo." (PMID 28646884, 2017).
infection (continued). "We further assessed BMDM responses during infection by measuring levels of secreted TNF and production of nitric oxide (as measured by medium nitrite levels)." (PMID 28278296, 2017). "The abortive EHV-1 strain KentuckyD induced an increased mRNA expression of different cytokines such as IFN-α, IFN-β, IFN-γ, and TNF-α in PBMC after infection." (PMID 28925977, 2017). "The analysis confirmed that this subset expanded during the infection and its frequency was higher in TNF KO mice compared with WT and tmTNF KI mice." (PMID 28890718, 2017). "The mRNA expression of TNFα revealed a strong induction during L2-MHV3 infection in WT and IL-33 KO mice, although enhanced expression was found in IL-33 KO mice especially at 48 h PI." (PMID 28607531, 2017). "Since UL45 and UL48 are expressed with early-late kinetics, their effects on TNFα-induced NF-κB activation were assessed 72 h after infection with wild-type or mutant viruses." (PMID 28570668, 2017). "Lack of HDAC6 also decreased the relative mRNA levels of the pro-inflammatory cytokines TNFα, IL-1β and IL12p40, indicating impaired cytokine activation after infection." (PMID 29281743, 2017). "At 96 h after infection, the mRNA expression of IL-1β was downregulated in all the organs (liver, kidney, and lung), while TNF-α was downregulated only in the kidney." (PMID 28791016, 2017). "TNF-α expression levels were high during the P.y-GPC3 infection on the 1st, 7th or 14th different days and were significantly different from those of uninfected mice (all P ≤ 0.01)." (PMID 28445973, 2017). "During infection, pro-inflammatory cytokines are released, specifically TNF, IL-1, IL-6 and IFN-g leading to increased expression of adhesion molecules on the surface of the vascular endothelium." (PMID 28202022, 2017). "Transcriptional regulation of CXCL10 following infection with Ad vectors, differs significantly from the transcriptional mechanisms activated in response to TNF-α and IFNγ." (PMID 28525366, 2017). "We therefore collected serum samples after infecting mice with of E. coli (2×108 CFU) by i.p. injection; serum was collected 1, 2.5, and 6 h after infection for measuring TNF-α, IL-6 and IFN-γ levels, respectively." (PMID 28815056, 2017). "A proportional relationship between antibodies and infection was found, but for appropriate diagnosis, TNF-α (Th1) and IL-4 (Th2) were measured." (PMID 28717322, 2017). "The mRNA levels of cytokines in Caco-2 cells measured by qRT-PCR revealed a dramatic increase of IL-1β, IL-8 and TNF-α after infection with S. typhimurium for 2 h." (PMID 29232851, 2017). "A comparison between cytokine MFI at peak parasitaemia and baseline (day 0) showed that TLR9-stimulated pDC expressed more IFN-α at peak-infection, whilst TNF production remained unchanged." (PMID 28572564, 2017). "We also expected to find evidence of T-cell activation, and evidence of an IFNγ and TNFα response profile since patients present several weeks after primary infection, and long enough for T-cell and IFNγ responses to have developed." (PMID 29140996, 2017). "TNF-α plays a key role in neutrophil recruitment in the inflammatory response to infections; nevertheless, it can also enhance bacterial growth." (PMID 28475641, 2017). "The synthesis and release of interferon, TNF, and ILs initiates inflammatory responses and directs neutrophil migration to the site of infection." (PMID 28255203, 2017). "The inflammation of mammary tissues after the onset of infection can be manipulated by many cytokines and inflammatory mediators such as tumor necrosis factor-α (TNF-α), interleukin 1β (IL1β), IL8, and prostaglandin F2α." (PMID 28507412, 2017). "Opportunistic infections should be highly suspected in immunosuppressed patients on medications like TNF-α inhibitors or corticosteroids." (PMID 28086756, 2017).
infection (continued). "Whereas IL-1β and TNF-α are the first cytokines in an infection and are generally pro-inflammatory, IL-6 is secreted thereafter and acts in both pro- and anti-inflammatory roles." (PMID 29078765, 2017). "When THP-1 cells were infected with Ms_PE_PGRS41 combined with a stimulatory dose of LPS, TNF-α, IL-6 and IL-1β expression were significantly increased compared to the response to LPS or Ms_PE_PGRS41 infection alone." (PMID 28440335, 2017). "Future work is clearly needed to disentangle the mechanisms of TNFα’s metabolic effects during infection." (PMID 29216326, 2017). "This pathway was previously demonstrated to amplify TNF signaling following infection with GBS, S. pneumoniae, and E. coli." (PMID 28894449, 2017). "Infections observed in adult patients treated with anti-TNF-α mAbs resemble those observed in patients with Mendelian Susceptibility to Mycobacterial Disease (OMIM 209950), caused by monogenic errors in the IL-12/IFN-γ pathway." (PMID 28983301, 2017). "Tumor necrosis factor (TNF) [previously known asTNF-α (TNF-α) orTNFA] is a pleiotropic cytokine that produced as a part of thehost defense against the infection." (PMID 28935761, 2017). "TNF expression is activated early after infection and signals through the TNFR1 and TNFR2 receptors." (PMID 28542390, 2017). "Given the important role of TNF-α in controlling the growth of T. gondii, infection with opportunistic pathogens such as T. gondii can be a major safety concern in patients receiving this therapy." (PMID 29065914, 2017). "However, current treatments for neuroinflammatory are monotherapies mostly, limited by well-known side effects as we know, COX-2 inhibitors may lead cardiovascular defects responded to long-term treatment, and TNF-targeted treatment could cause infection through immunosuppression." (PMID 29180652, 2017). "SS1/SS1 infection exhibited highest level of TNF-α and IL-1β expression as compared to other groups." (PMID 28286572, 2017). "B. canis replication was confirmed in infected placental explants and the infection elicited an increased secretion of TNF-α, IL-8, IL-6 and RANTES." (PMID 29036184, 2017). "At onset of infection, serum levels of both pro- (TNFα, IL6, IL8) and anti-inflammatory (IL10) cytokines were significantly lower in SIRS-N compared to SIRS-P patients." (PMID 31058274, 2017). "Neutrophils and MΦ express iNOS, release reactive oxygen species (ROS) and TNFα in the infection with R. typhi, and death of the animals can be ascribed to overwhelming systemic release of inflammatory cytokines." (PMID 28770333, 2017). "Especially important for the restriction of initial infection, TNF was demonstrated to elicit expression of chemokines and adhesion molecules that are needed for the recruitment of neutrophils to the infection site." (PMID 29062811, 2017). "Analysis of mRNA levels of IL-6 and other pro-inflammatory cytokines and chemokines at 2.5 h, 4 h and 8 h post infection (p.i.) revealed a moderate induction of IL-6, TNFα, CCL3 and CCL5 upon IV infection of Calu-3 cells." (PMID 28195157, 2017). "This is often associated with increase in mostly Th1 cytokines (including IFN-γ and TNF-α) which are important for effective clearance of parasites during the early stage of infection." (PMID 28769924, 2017). "qPCR data showed uniform down-regulation of TNF in Met-5A cells whereas primary mesothelial cells displayed a strong dose-dependent signal early after infection." (PMID 28542390, 2017). "Antibiotic treatment of TNFα-depleted animals prevented the escalation of the infection to high numbers that would otherwise lead to the rapid death of the animal." (PMID 28087648, 2017). "mRNA levels of IL-1β and TNF-α genes are down-regulated in rainbow trout after infection with Aeromonas salmonicida." (PMID 28542591, 2017). "The study established cutoffs facilitating diagnosis on day one of infection: IL-6: 31 pg/mL; TNF-α: 17 pg/mL; IL-1β: 1 pg/mL." (PMID 28487810, 2017).
infection (continued). "Markers of inflammation including neutrophil infiltration and proinflammatory cytokine production in the BALF, such as TNF-α, IL-1β and IL-6, were determined 8 and 24 hours post-infection." (PMID 28638106, 2017). "Although 42–65% of patients understood they should temporarily halt anti-TNF therapy with concurrent infection, 75% of patients recalled continuing therapy despite infection." (PMID 28526972, 2017). "After adjusting for age, children in the middle/highest strata of Vδ2+ T cell IFNγ/TNF co-production had a significantly higher odds of submicroscopic infection if infected than children in the lowest strata (OR 1.46, 95% CI 1.01–2.11, P = 0.04)." (PMID 28904345, 2017). "TNF-α and IL-8 have been found to be pivotal in overcoming infection by Mycobacterium tuberculosis, enabling macrophages to form granulomas." (PMID 28986583, 2017). "Our result suggested that Th1 cytokines, TNF-α and IL-1β expression increased in cag+ infection compared to cag− infection." (PMID 28286572, 2017). "TNF-α attracts neutrophils, which are the principle phagocytic cells, to the site of infection by upregulating chemokines, such as IL-8, and facilitates diapedisis through the upregulation of cell adhesion molecules." (PMID 28978916, 2017). "Classical proinflammatory cytokines of early response such as IL-6 or TNF-α were also significantly induced due to infection." (PMID 29348965, 2017). "Mtb is endowed with the unique ability to regulate fundamental inflammatory processes, such as recruiting immune cells to the focus of infection to produce proinflammatory cytokines (IL-1β, TNF-α, etc.)." (PMID 28642632, 2017). "Early after infection, TNFα, IL-1β, IL-6, IL12p70 and IFN-β levels were lower in supernatants from Hdac6-/- cells than in those from Hdac6+/+ cells, and this difference held at 12 and 24 hpi." (PMID 29281743, 2017). "Serum was isolated from the blood obtained by bleeding the mice retro-orbitally two hours post infection and ELISA was performed to determine the amount of TNF-α produced in the untreated group and the peptide-treated group." (PMID 28611397, 2017). "In vivo, we found that that the expression levels of IL-2, IL-4, IL-6 and TNF-a in the lungs of H9N2 infected mice peaked on 2 days post-infection and then declined on days 4 and 6 post-infection." (PMID 28114957, 2017). "For example, during infection with a more virulent P. yoelii variant, CTLA-4 blockade induced markedly increased serum levels of TNF-α accompanied by severe inflammation and reduced survival." (PMID 28894272, 2017). "There are earlier reports also which depict that infection with live, virulent promastigotes leads to the release of preformed β-hexosaminidase and TNF-α and de novo synthesis of TNF-α in BMMCs10." (PMID 29038500, 2017). "MuV significantly increased CXCL10 levels in the media of both WT and TNF-α−/− cells; however, the CXCL10 level in TNF-α−/− cells was significantly lower than that in WT cells in response to MuV infection." (PMID 29072682, 2017). "These cytokines bind to specific cell surface receptors (IL-1R for IL-1β and TNFR1 or TNFR2 for TNF-α) after release from activated macrophages and/or T cells at the site of infection." (PMID 28270578, 2017). "We found that ZIKVC infection was enhanced in 3-D-cultured cells exposed to purified TNF-α compared to mock-treated controls." (PMID 28656176, 2017). "The treatment with either antibiotic induced a steeper decline of bacterial numbers in the organs of anti-TNFα-treated mice compared to IgG-treated mice, leading to similar bacterial loads in the two groups of animals by day 8 post-infection." (PMID 28087648, 2017). "The infection stimulated the release of TNF-α, IL-1β, IL-6, IL-8, and IL-10 production by infected cells." (PMID 29118740, 2017). "In the present study we focused on the TNF-α pathway of inflammation because of its importance in this infection." (PMID 29190292, 2017).